CDX2 (caudal type homeobox 2)
Diseases named in the same sentence as CDX2 in open-access papers (continued):
Sharing a sentence is not in itself a finding about the gene and the disease.
colon carcinoma (continued). "Histological findings including the immune-histochemical examinations (CK7−, CK20+, CDX2+ and SATB2+) uncovered the metastatic tumor into extrahepatic bile duct originated from the primary colon cancer." (PMID 32975689, 2020). "Our results show that CDX2 expression influences the adhesion ability of cultured colon cancer cells, and indicates that adjustments in CDX2 expression levels in cancer cells during EMT and MET is vital in the metastatic process of colon cancer." (PMID 32408894, 2020). "Taken together, our observations support the positive correlation between CDX2 and SI as well as the negative regulatory action of CDX2 on the designated Wnt targets AXIN2, cMYC, and CYCLIND1 in colon cancer cells." (PMID 32814764, 2020). "CDX2 and VDR expression level in the three sub-clusters of colon cancer patients were also significantly different." (PMID 31596728, 2019). "For example, both VDR and CDX2 are highly expressed in chemotherapy, BRAF inhibitors and PI3K-mTOR inhibitors resistant colon cancer cells." (PMID 31596728, 2019). "All those results suggest that similar with CDX2, VDR is also an important prognostic biomarker for colon cancer patients." (PMID 31596728, 2019). "IHC stains such as TTF-1, CDX2, CK7, and CK20 help distinguish metastatic lung carcinoma from primary colonic cancer." (PMID 30961608, 2019). "CDX2 transactivates the expression of GSK-3β and Axin2 to inhibit the cell proliferation and tumor formation in colon cancer." (PMID 31200542, 2019). "We found that CDX2 was highly expressed in docetaxel, cisplatin, temsirolimus, dabrafenib and PIK-93 resistant colon cancer cells." (PMID 31596728, 2019). "By immunohistochemistry, the cell line was proven to express the biomarkers of colon cancer CK20 and CDX2, while a-fetoprotein, hep-1 and glypican-3 were stained negative, which demonstrated that the HCS1220 cell line originating from the intestinal tissue." (PMID 30214379, 2018). "By immunohistochemistry, HCS1220 was proven to express the biomarkers of colon cancer CK20 and CDX2." (PMID 30214379, 2018). "In the case of colon cancer, silenced TFs included well known intestinal differentiation factors such as CDX1, CDX2 and NEUROD1." (PMID 27562343, 2016). "In CDX2 and CK20, the ground truth images metastasis of colon cancer is colored completely or partially brown, whereas the hepatocytes and inflammatory cells are colored blue." (PMID 26099963, 2015). "In this study we showed CDX2 expression in about one third of PDAC and the expression pattern is weak and heterogeneous in contrast to the strong and homogeneous pattern seen in colon cancer." (PMID 24489794, 2014). "Here, we demonstrate by confocal microscopy that CDX2/AS co-localizes with the well-established SR proteins ASF/SF2 and SC35 in 293T and RKO colon cancer cells." (PMID 25101906, 2014). "It stained positive for cytokeratin 20, CDX2, and CEA, as colonic cancers do, but was also immunoreactive for cytokeratin 7 and p16, which are characteristic for the female genital tract neoplasms." (PMID 24307962, 2013). "Our further studies using full length and/or deletion mutant constructs in two different human colon cancer cell lines, SW480 and HCT116, showed key role of Cdx1, Cdx2 and GATA4 in the regulation of claudin-1 mRNA expression." (PMID 22719836, 2012). "Taken together, we conclude that homeodomain transcription factors Cdx1, Cdx2 and GATA4 regulate claudin-1 gene expression in human colon cancer cells." (PMID 22719836, 2012). "Using human colon cancer-derived cells, we found that baicalein, in contrast to baicalin, induces PXR through Cdx2." (PMID 22815676, 2012). "We observed a similar trend of induction of pGL3/−1.2Cld-1-driven luciferase activity in HCT116 colon cancer, which was 2.5–3 fold upon overexpression of Cdx1 and GATA4 and ∼4-fold upon overexpression of Cdx2." (PMID 22719836, 2012).
colon carcinoma (continued). "To directly assess the impact of CDX1 and CDX2 on MS4A12 transcript and protein expression we silenced both factors in LoVo and SW48 colon cancer cells by transient transfection with specific siRNA duplexes." (PMID 19781065, 2009). "A test for interaction between CDX2 level and adjuvant chemotherapy in stage II colon cancer was not statistically significant (p = 0.98)." (PMID 39201360, 2024). "About 90% of colon cancers express CDX2 and have a better prognosis than CDX2-negative colon cancers." (PMID 39452477, 2024). "CDX2, CK20, β-catenin, PSA, P501S, and P504S may help to further differentiate prostate carcinoma from colon carcinomas in immunohistochemistry of poorly differentiated cancer involving the colorectal-prostatic region." (PMID 36930066, 2023). "In this way, LIN28B promotes transformation and migration in colon cancer through LGR5, PROM1, and CDX2 mRNAs, promotes stemness and EMT in gastric cancer through NRP-1 mRNA, inhibits apoptosis in ovarian cancer through AKT2 mRNA, and promotes migration in neuroblastoma through MYCN-induced mRNAs." (PMID 37370851, 2023). "Moreover, exosomal miR-24-3p can be transferred from CAFs to colon cancer cells and down-regulate CDX2/HEPH axis, resulting in significantly enhanced resistance of colon cancer cells to methotrexate (MTX)." (PMID 35574420, 2022). "Squamous cell lesions of unknown origin have been observed in colonic polyps of CDX2-knockout mice, and likewise in SMAD3-depleted and SMAD3-knockout colonic tumors given DSS compared to DSS alone." (PMID 35600339, 2022). "Importantly, CDX2 depletion greatly blocked the inhibitory effects of GSK126 and OCA on the proliferation and invasion of colon cancer cells." (PMID 35449124, 2022). "Currently, there is minimal literature on CDX2 influencing adjuvant therapy in stage II colon cancer and its role in prognostication has not yet been established." (PMID 35323316, 2022). "CDX2, a CRC-specific nuclear marker in almost 100% of colon tumor organoids, was expressed." (PMID 35721501, 2022). "For example, CDX2 was identified through a bioinformatics approach and proved to be prognostic and predictive for the efficacy of adjuvant chemotherapy in patients with stage II and III colon cancer." (PMID 36010837, 2022). "The aim of this study was to explore the expression patterns of HLA-G, PD-L1, and CDX2 as well as CD3 and CD8 in a cohort of patients diagnosed with pT3 and pT4 colon cancers, and to investigate their value as prognostic markers individually and in a combined model." (PMID 35027037, 2022). "A context‐dependent activity of CDX2 has already been described regarding its nontranscriptional activity on DNA repair between colon cancer and leukemia cells." (PMID 33960108, 2021). "In this case, the poorly differentiated carcinomatous component was positive for epithelial and colon cancer markers (CK7, CK20, EMA, CDX2, and AFP) and the spindle-shaped pleomorphic sarcomatous component was strongly positive for vimentin, but negative for epithelial markers." (PMID 33765265, 2021). "CDX2 is usually negative for primary ovarian cancer, whereas CDX2 is positive for ovarian metastases from the colon cancer or gallbladder." (PMID 34348771, 2021). "All these results indicated that CDX2 could bind to the P1 fragment of the PTEN promoter and transcriptionally activate PTEN in colon cancer cells." (PMID 33239678, 2021). "Furthermore, CDX2 and SATB2 are a highly sensitive and specific markers for metastatic lesions of gastrointestinal tract adenocarcinoma, especially colon cancer." (PMID 32975689, 2020). "The samples of pre- and postoperative serum was applied to wild type colon cancer LS174T cells and CDX2 inducible LS174T cells and adhesion was measured with Real-Time Cell-Analysis iCELLigence using electrical impedance as a readout to monitor changes in the cellular adhesion." (PMID 32408894, 2020).
colon carcinoma (continued). "The aim of this study was to examine the effect of surgery on adhesion of cultured colon cancer cells with or without expression of the tumour suppressor CDX2." (PMID 32408894, 2020). "A subgroup of colon cancer patients with lack of CDX2 expression preferentially benefits from adjuvant chemotherapy." (PMID 31596728, 2019). "Furthermore, our study demonstrated that CDX2 specifically and directly binds to the GSK-3β promoter and the Axin2 upstream enhancer in colon cancer cells, by qChIP." (PMID 30631044, 2019). "All those VDR expression features were quite similar with CDX2, so we speculated that VDR was also an important prognostic biomarker for colon cancer patients." (PMID 31596728, 2019). "Moreover, immunohistochemical staining showed that these lesions were positive for poorly differentiated colon cancer markers (CK20, CDX2, AE1/AE3), and lung cancer markers (TTF1 and Napsin)." (PMID 31200749, 2019). "Our observation that induced CDX2 expression in LS174T cells promotes an increased ST14/SPINT1 ratio does not correlate with the reported expression pattern of decreased CDX2 levels and increased ST14/SPINT1 levels during colon cancer progression." (PMID 30087389, 2018). "Notably, mutation of a subdomain in the N-terminus of CDX2 has been reported to abrogate the anti-proliferative effects of CDX2, which may be via inhibition of β-catenin/T-cell factor (TCF) transcriptional activity by disrupting the β-catenin-TCF protein complex in colon cancer cells." (PMID 25847407, 2015). "CDX2/AS altered splicing patterns of CD44v5 and Tra2-β1 minigenes in Lovo colon cancer cells independent of CDX2 expression." (PMID 25101906, 2014). "In colon cancers, KLF4 could be down-regulated by caudal type homeobox 2 (CDX2), notch signaling, transcription factor 4 (TCF4) or sex determining region Y-box 9 (Sox9)." (PMID 22937066, 2012). "RNA interference (RNAi)-mediated silencing of intestine-specific transcription factors CDX1 and CDX2 and chromatin immunoprecipitation (ChIP) in LoVo and SW48 colon cancer cells revealed that MS4A12 transcript and protein expression is essentially dependent on the presence of endogenous CDX2." (PMID 19781065, 2009). "However, giving additional chemotherapy after surgery to certain early-stage colon cancer patients with low CDX2 levels did not significantly improve survival." (PMID 39201360, 2024). "However, this is less clinically meaningful, as most stage III colon cancer patients would be recommended for adjuvant chemotherapy regardless of CDX2 expression." (PMID 39201360, 2024). "Currently CDX2 is not utilised in prognostication in colon cancer in the clinical setting." (PMID 35323316, 2022). "Moreover, in individuals treated with adjuvant chemotherapy, CDX2-negative colon cancers in stage II were found to have a significantly increased five-year DFS (91%) in comparison with those who did not undergo adjuvant chemotherapy (56%)." (PMID 35055034, 2022). "In addition, the rate CDX2-negative samples were significantly higher in right colon cancer and in patients with CRC and Por/Sig/Muc histology and confirms the results of several recent reports." (PMID 31783700, 2019). "In addition, the colon cancer marker CDX2 protein were also not found to be expressed on original GBC." (PMID 31367188, 2019). "In the nonmucinous type of colon cancer, decreased MUC2 expression was found, and expression was found to be suppressed by the transcriptional factor caudal type homeobox 2 (CDX2), which may have been caused by the high methylation modification of the promoter of the MUC2 gene." (PMID 32695780, 2020). "Immunohistochemical studies showed that the liver tumor and primary colon cancer were negative for cytokeratin (CK) 7 and positive for CK20 and Caudal-type homeobox transcription factor 2 (CDX-2)." (PMID 30658608, 2019).
colon carcinoma (continued). "AFP, hep-1 and glypican-3, the well-used biomarkers for HCC, were negative and two well-known tumor markers for colon cancer, CK20, CDX2 were positive, clearly indicating that xenograft tumor were derived from intestinal tissue." (PMID 30214379, 2018). "Meanwhile, the primary colon cancer was also positive for CK20 and CDX-2, but negative for CK7." (PMID 30658608, 2019). "Typical human colon cancer tissues are positive for CK20 and CDX2, and negative for CK7." (PMID 25006808, 2014). "Our study identified significantly increased cell adhesion abilities in five different colon cancer cell lines in postoperative serum, and further investigation using genetically modified LS174T cells showed this increase in adhesion to be eliminated by lack of CDX2 expression." (PMID 32408894, 2020).
gastric cancer (104 papers, 2006 to 2025). A primary or metastatic malignant neoplasm involving the stomach. "Another pathway with a significant role in CDX2 regulation, the Hippo pathway, showed a lower prevalence of mutations in gastric cancers." (PMID 40149431, 2025). "Mutations in APC were also frequent in gastric cancers with CDX2 induction and SOX2 suppression (16.2% of cases), and the difference in prevalence compared with SOX2-maintained-expression cancers approached significance (Fisher’s exact test with p = 0.06)." (PMID 40149431, 2025). "The metaplastic intestinal program associated with CDX2 up-regulation in the stomach increases the risk for the acquisition of additional molecular alterations that lead to intestinal-type gastric cancers." (PMID 39768557, 2024). "In contrast, the gene encoding for the alpha catalytic sub-unit of kinase PI3K, PIK3CA, was more frequently mutated in gastric cancers with lower expression of CDX2 (29% versus 16% in cancers with higher CDX2, Fisher’s exact test p = 0.02)." (PMID 39768557, 2024). "The association between CDX2 and Reg IV in gastric cancer tissues was analyzed using χ2-test and Spearman’s rank correlation." (PMID 33639844, 2021). "Correlation analysis further showed that the expression of CDX2 mRNA was positively associated with that of Reg IV mRNA in gastric cancer tissues (r = 0.387, p = 0.0001)." (PMID 33639844, 2021). "Further analysis showed that the expression of the CDX2 protein was positively associated with that of the Reg IV protein in gastric cancer tissues (r = 0.334, p = 0.001)." (PMID 33639844, 2021). "A previous study evaluated the expression levels of CDX2 and its association with the clinicopathological characteristics of gastric cancers, but the independent prognostic value of CDX2 remains controversial." (PMID 29179508, 2017). "Although several lines of evidence have indicated that CDX2 is a potential tumor suppressor gene in ovarian, gallbladder, colon and gastric cancer, the mechanisms associating the overexpression of CDX2 with gastric cancer remain to be elucidated." (PMID 25738600, 2015). "The association of Sox2 and Cdx2 genes has also been shown in a different system, that of gastric cancer where Sox2 and Cdx1/Cdx2 are inversely related." (PMID 21103067, 2010). "The increased rate of mutations in the WNT/APC/β-catenin pathway observed in CDX2-induced gastric cancers with SOX2 suppression may serve to reinforce CDX2 expression in these cancers, as WNT signaling is an inducer of CDX2 transcription." (PMID 40149431, 2025). "Furthermore, gland structure in antral tumors, together with the ectopic expression of CDX1, CDX2 and Villin, the well-known intestinal epithelial markers, suggested that gastric cancer caused by Prmt5 deletion was intestinal-type gastric cancer." (PMID 35864961, 2022). "Interestingly, a recent study indicated that CagA disrupts tight junctions by increasing the CDX2-dependent targeting of Claudin-2 in gastric carcinoma cells and causes significant changes in the morphology and activity of these cells." (PMID 35331316, 2022). "Ectopic expression of CDX2 is associated with the development and progression of gastric cancer." (PMID 33639844, 2021). "There are some reports that intestinal-type cancer is proportionately more common in men and the fact that Cdx2 is associated with differentiated gastric carcinoma may help to explain our results." (PMID 23181722, 2012).